BRCA2 (BRCA2 DNA repair associated)
Diseases named in the same sentence as BRCA2 in open-access papers (continued):
Sharing a sentence is not in itself a finding about the gene and the disease.
cancer (continued). "BRCA2-deficient cancer cells displayed an increased sensitivity towards TRAIL-R-targeting agents." (PMID 26843614, 2016). "However, also somatic mutations of BRCA2, which are considered here, have been shown to drive cancer progression." (PMID 25569148, 2015). "An additional strength was that our model incorporated the risks of death from the key cancers associated with BRCA2 mutation, breast and ovarian, into all-cause mortality rates, thereby providing more accurate estimates for life expectancies within this unique cohort of patients." (PMID 26844277, 2015). "Genetic or epigenetic inactivation of MCM8-9 is a new mechanism by which cancers can blunt the HR repair pathway, and as in cancers with mutations in BRCA1 or BRCA2, cancers that inactivate MCM8-9 are susceptible to chemotherapy agents that target cells with blunted HR." (PMID 26215093, 2015). "Thus, even though loss of EEPD1 results in genomic instability, EEPD1 should not be viewed as a tumor suppressor in the same sense as BRCA1 and BRCA2, two HR components that show loss of function mutations in cancer." (PMID 26684013, 2015). "In conclusion, we showed that multiplex PCR followed by NGS is useful for screening BRCA1 and BRCA2 germline mutations of probands and could be applicable to cancer prevention in unaffected relatives carrying the same mutation." (PMID 25802882, 2015). "Loss of this control owing to BRCA2 or Rad51 mutations may lead to gross chromosomal rearrangements and increased susceptibility to cancers." (PMID 25938495, 2015). "However, BRCA1 or BRCA2 are not only inactivated through gene mutation, also DNA hypermethylation of the genes is frequently reported for several cancers." (PMID 25852742, 2015). "The present study provides support for the clinical use of new treatment drugs, and is the beginning of the potential application of flavonoids in cancer prevention and the periodic consumption of appropriate flavonoids to reduce cancer risk in individuals carrying a mutant allele of the BRCA2 gene." (PMID 24317580, 2014). "Accumulating studies have indicated that the polymorphic variants in BRCA2 gene may also confer genetic susceptibility to cancer because of the alteration in DNA repair capacity." (PMID 25348552, 2014). "The N372H polymorphism in the exon 10 is the only identified common non-synonymous polymorphism in BRCA2 gene, which may confer genetic cancer predisposition." (PMID 25348552, 2014). "Interestingly, human cancer syndromes linked to heritable BRCA2 mutations are also limited to a small range of tumor types." (PMID 24489863, 2014). "Thus, murine models that recapitulate the effect of cancer‐associated mutations in human BRCA2 on tissue‐specific carcinogenesis provide an important opportunity to dissect the complex roles played by chromosomal instability during human carcinogenesis." (PMID 24268522, 2014). "Thus, PARP1 inhibitors should be reserved for clinical use when BRCA2 LOH can be verified in the tumour, assessment of which emerges as a critical requirement in the design of human clinical trials for the treatment of BRCA2‐deficient cancers." (PMID 24268522, 2014). "We propose that the new natural agents may have the potential of reducing cancer risk by the elimination of BRCA1 or BRCA2 homozygous mutated cancers." (PMID 24317580, 2014). "Most of the deleterious BRCA1 and BRCA2 variants characterized thus far introduce stop codons or frame-shifts that result in premature truncation of the protein, the consequences of which manifest as cancer at relatively early ages." (PMID 25011685, 2014). "BRCA2 mutation in humans is associated with two distinct cancer susceptibility syndromes." (PMID 24489863, 2014). "A Phase I clinical trial of patients with solid tumors using MK-4827 was shown to have favorable pharmacokinetics, inhibited PARP activity effectively, is well tolerated and has anti-tumor activity in carriers of BRCA1 and BRCA2 mutations and patients with sporadic cancers." (PMID 24795863, 2014).
cancer (continued). "However, the rationale for the use of targeted agents such as PARP1 inhibitors (PARP1i) in BRCA2‐deficient cancers is contingent upon bi‐allelic BRCA2 inactivation in the tumour cells." (PMID 24268522, 2014). "Here, we will review this question from the perspective of recent work using transgenic models designed to recapitulate a specific human cancer involving mutations affecting the tumour suppressor gene BRCA2, associated with hereditary predisposition to breast, ovarian, pancreatic and other cancers." (PMID 24268522, 2014). "Mutations in ATM (Ataxia Telangiectasia Mutated), MRE11, NBS1 (Nijmegen Breakage Syndrome), BRCA1 (Breast Cancer 1), BRCA2 and Ligase 4 cause human syndromes characterized by both CABs and cancer predisposition, highlighting the connection between CABs and cancer." (PMID 24651653, 2014). "This suggests that hypoxia may already play a role in the DCIS stage of BRCA1 and BRCA2 germline mutation related breast carcinogenesis, and may also drive cancer progression." (PMID 23409121, 2013). "Loss of RAD52 function is synthetically lethal with BRCA2 deficiency in human cancer cell lines." (PMID 23675572, 2013). "This suggests that hypoxia may already play a role at the DCIS stage of BRCA1 and BRCA2 germline mutation-related breast carcinogenesis, and may also drive cancer progression." (PMID 23409121, 2013). "Recently, next generation (exome) sequencing of 316 OC revealed that over 20 percent of these cancers carried either somatic or germline inactivating mutations in either BRCA1 or BRCA2, thus emphasizing the importance of these two genes in the pathogenesis of OC." (PMID 23522120, 2013). "In the BRCA2 gene, N372H (rs144848) which results in an amino acid change is the most common polymorphism with a minor allele (C) frequency of 27% among Caucasian cancer patients." (PMID 23964347, 2013). "The association with survival was similar in cancers with either BRCA1 or BRCA2 mutations." (PMID 24265793, 2013). "The carriers had high grade carcinomas of different histopathological types: serous (case diagnosed at 61 years) and endometrioid (case diagnosed at 54 years) subtypes, where the latter carrier also harbored a BRCA2 mutation." (PMID 23302520, 2013). "This would give rise to cancer cells with BRCA2 deficiency, thereby leading to accelerated mutation rates and, through the forces of natural selection, advantageous changes could accumulate and eventually lead to disease progression." (PMID 21958427, 2011). "We have therefore sought to test whether our atomistic simulations of BRCnA-RAD51 complexes might reveal information concerning the ability of cancer-associated BRCA2 alterations to affect the interaction between BRCA2 and RAD51." (PMID 21789034, 2011). "Three of these four cancers (7.3% overall) were considered germ-line mutations (with confirmation in normal tissue) suggesting that the rate of germ-line BRCA2 mutations in apparently sporadic pancreatic cancer may be as high as in breast or ovarian cancer." (PMID 22312493, 2011). "The considerable uncertainty regarding cancer risks associated with inherited mutations of BRCA2 is due to unknown factors." (PMID 21060860, 2010). "Our results suggest that the high grade ER+ luminal cancers also may be enriched for tumors with BRCA1 or BRCA2 deficiency." (PMID 21080930, 2010). "Given that the second BRCA2 allele is consistently deleted from cancer cells, we used gene targeting to introduce the corresponding P3240L mutation into one allele of GgBrca2, while deleting the second allele, to recapitulate cancer-associated genetic alterations." (PMID 19540122, 2009). "In the last decade, several reports have been published supporting the hypothesis that different mutations in the BRCA1 or BRCA2 genes confer different cancer-related risks." (PMID 19329713, 2009).
cancer (continued). "All BRCA1 and BRCA2 pathogenic mutations resulted in gene expression changes relating to cell cycle, cancer and cellular growth and development, while BRCA1 and BRCA2 missense mutations shared some additional similarities (cell death and cell development pathways)." (PMID 18497862, 2008). "In fact, the analysis of only 4 PCR fragments (1806C>T, exon 5 (300T>G, 300T>A), 5382insC in the BRCA1 gene and IVS16-2A>G in the BRCA2 gene) would lead to the identification of the cancer predisposing mutations in 67% of the BRCA1/2 mutation-positive families." (PMID 18783588, 2008). "The -26 G>A polymorphism in the 5' UTR of BRCA2 has been analyzed in some cancer types." (PMID 17945002, 2007). "In addition, many Brca1- and Brca2-deficient mouse models with cancer susceptibility have been generated." (PMID 18047734, 2007). "Somatic mutations of BRCA2 are rare in typical sporadic cancers." (PMID 16417627, 2006). "Participants consisted of 339 Australian Ashkenazi Jewish women who provided a blood sample for research used to test for Ashkenazi Jewish ancestral mutations in the genes BRCA1 and BRCA2, and were offered their genetic test result through a cancer genetics service." (PMID 17102813, 2006). "The risk factors for BRCA1 and BRCA2 cancers appear to be different." (PMID 16563180, 2006). "A heterozygous BRCA2 variant was present in 13% of the women with predominantly intraductal cancer." (PMID 16280055, 2005). "Variation in the penetrance estimates for BRCA1 and BRCA2 mutation carriers suggests that other genetic polymorphisms may modify the cancer risk in carriers." (PMID 15138485, 2004). "Similarly, other cancers are over-represented providing additional evidence that BRCA2 mutations result in a less restricted disease phenotype than BRCA1 mutations." (PMID 12373604, 2002). "Variation in the penetrance estimates for BRCA1 and BRCA2 mutations carriers suggests that other genetic polymorphisms may modify the cancer risk in carriers." (PMID 11437399, 2001). "A strong Bcl-2 expression was found in the four cases of Brca2 -associated carcinomas." (PMID 11044356, 2000). "The decreased BRCA1 and BRCA2 expression in this cell line are mainly due to its aggressive phenotype and defective DNA repair mechanism, which ultimately contribute to genomic instability, an important hallmark of cancer progression and therapeutic resistance." (PMID 40661795, 2025). "Collectively, these data demonstrate that BRCA2 deficiency significantly increases tumor sensitivity to V66-exatecan, promoting tumor regression and significantly improving survival, highlighting the potential of V66-exatecan as an effective therapeutic strategy for BRCA2-deficient cancers." (PMID 41077566, 2025). "Furthermore, other nongenetic risk factors such as diet, physical activity, alcohol and tobacco, hormonal exposures, as well as radiation and pollution may also contribute to the variability of cancer risk among BRCA2 PV carriers." (PMID 40462315, 2025). "A very recent study analyzing the prevalence of germline cancer susceptibility variants in patients with periampullary cancers showed that among 69 patients with duodenal cancer, 9 had a pathogenic germline variant, including three with a pathogenic/likely pathogenic germline variant in BRCA2." (PMID 40205657, 2025). "Moreover, a somatic screening for BRCA2 variants at the time of cancer diagnosis could have influenced the medical management of our patients, including the consideration of risk‐reducing surgery and/or treatment with a PARPi." (PMID 40205657, 2025). "However, the genomic location and specific mechanisms by which BRCA2 prevents transcription-associated DNA damage and genomic instability in cancers remain unclear." (PMID 38830843, 2024).
cancer (continued). "This could be expected to be different if cancer predisposition genes such as BRCA1 or BRCA2 were included in the return of SFs, as in a recent paper from the BabySeq project, where the return of a genomic finding in children led to risk reducing surgeries in parents." (PMID 38740897, 2024). "Accordingly, the decreased sensitivity of the PEO4 cells to DNA damage may be primarily due to their functional DNA repair machinery resulting from the reversion of the BRCA2 mutation, which confers platinum resistance by restoring genome stability allowing the cancer cells to proliferate." (PMID 37958311, 2023). "Additionally, as an increasing number of targeted therapies are being developed, cfDNA analysis may be able to identify cancers eligible for personalized approaches (such as HER2 or BRAF targeted therapy or platinum-based chemotherapy for BRCA2 mutated PC)." (PMID 37685923, 2023). "Whereas in the past, germline testing focused on specific genes such as BRCA1 or BRCA2 to evaluate risk of breast, ovarian, and other cancers, over the past decade, there has been a shift to using multi-gene cancer panel tests that can reveal inherited risk for one or more cancer types." (PMID 37435610, 2023). "In addition, BRCA2 is a key tumor suppressor, with a plethora of mutations found in various types of cancers, with thousands of genetic variants of unknown significance (VUS) in the gene." (PMID 36702902, 2023). "The physiological impact and cancer risk of BRCA2 R3052Q variant remains unclear." (PMID 37980415, 2023). "The most important genetic markers of breast cancer are defined as breast cancer gene 1 (BRCA1) and breast cancer gene 2 (BRCA2) mutation genes, which are the most powerful predictive tools to identify patients suffering from breast and ovarian cancer with a 40%–80% risk of developing cancer." (PMID 37213283, 2023). "Hence, synthetic lethal avenues that diverge from PARPi could provide efficient therapeutic alternatives for treating BRCA2-deficient cancer cells." (PMID 37073955, 2023). "Since the first reports of pathogenic variants in BRCA1 and BRCA2, the breast- and ovarian cancer-predisposing genes (CPGs), almost 30 years ago, it is increasingly evident that there are unlikely to be other major high-risk genes contributing to these cancers." (PMID 36833203, 2023). "Besides, inherited mutations in BRCA1 or BRCA2 predispose to breast, ovarian, and other cancers." (PMID 36268271, 2022). "The shift in CLU+/SMA+ CAF ratios in human patients, and the shift in Clu vs. Acta2 expression in PSCs conditioned by Brca2-deficient cancer cells, suggest that CAFs of BRCA-mutated tumors may undergo a shift from myofibroblastic to immune-regulatory functions." (PMID 36316305, 2022). "In the present study, we confirmed the presence of true pathogenic germline variants only in BRCA2, which could possibly be due to the following reasons: First, BRCA2 was the most common cancer susceptibility gene in patients with advanced cancers who undergo universal germline sequencing." (PMID 35870019, 2022). "Furthermore, a diet rich in GSH-precursors might delay cancer onset in healthy BRCA2-mutation carriers by limiting FA toxicity." (PMID 35136057, 2022). "With the development of PARP inhibitors for treatment of cancer patients with an altered BRCA1 or BRCA2 gene, there is an urgent need to ensure that there are appropriate strategies for identifying mutation carriers whilst balancing the increased demand for and cost of cancer genetics services." (PMID 35143328, 2022). "Notably, the synergism could be observed not only in BRCA2-deficient cancer cells but also in their BRCA2 proficient counterparts in three independent models." (PMID 36358659, 2022). "Thus, although collaborative efforts have unified the information of BRCA2 mutations, most remain unknown for cancer risk." (PMID 34065235, 2021). "Therefore, we examined if WRN helicase inhibition induced DSBs in BRCA2-mutated cancer cells." (PMID 34772932, 2021).
cancer (continued). "However, the BRCA2 functional defect in cancer cells could be truncation, mutation, or secondary mutation." (PMID 33922657, 2021). "However, recent studies have identified that the cancer risk is similar to that of BRCA2 mutations." (PMID 34439348, 2021). "Hence, early identification of germline mutations in BRCA1 and BRCA2 genes may be relevant for management of patients with PrCa and also for preventing future cancers in their relatives." (PMID 34242281, 2021). "Mutagenic treatments may also accelerate the evolution of resistance in the primary tumours, as demonstrated by cisplatin-induced reversion mutations in BRCA2-deficient cancers, especially if DNA repair deficiencies in the tumours increase the mutagenicity of the treatment." (PMID 33502495, 2021). "Furthermore, a previous report has found that BRCA2-associated cancers are mainly PR positive." (PMID 34490083, 2021). "Targeting RAD52 could be a potential personalized therapy for BRCA2-deficient cancer." (PMID 33922657, 2021). "However, BRCA1 mutated cancers had higher expression compared to the BRCA2 mutant subset." (PMID 34465787, 2021). "Patients with BRCA2 mutations may develop genetic alterations leading to cancer." (PMID 33643409, 2020). "However, further studies are needed to determine whether this mechanism could also apply to BRCA2-associated cancer." (PMID 33299637, 2020). "Therefore, even though we report findings of previously undiscovered pathogenic germline variants, particularly in BRCA1 and BRCA2, the potential clinical benefit of PARPi treatment in these drug-resistant patients at advanced stage of cancer remains unclear." (PMID 31263571, 2019). "Similarly, PALB2 (partner and localizer of BRCA2), a binding partner of BRCA2 (breast cancer type 2 susceptibility protein), was found to directly interact with KEAP1 and induce NRF2 nuclear accumulation followed by antioxidant gene expression in HEK293 and U2OS cells." (PMID 31097977, 2019). "Thus, an unrecognized function of BRCA2 in regulating transcription elongation is subverted by cancer-causing mutations, in turn provoking the site-specific accumulation of genome-destabilizing R-loops, which can be cleaved by the ERCC4 endonuclease into DNA breaks." (PMID 29386125, 2018). "Thus, we have found six intronic and two missense BRCA2 variants which alter the splicing and could confer cancer risk." (PMID 29881398, 2018). "Mice and cells that express BRCA2 deleted for the exon 27 encoded region exhibit hypersensitivity to γ-radiation, premature replicative senescence, chromosomal instability, increase in the levels of stalled RFs and a reduction in survival due to an early onset of cancer." (PMID 31435521, 2018). "BRCA2 mutations in humans increase susceptibility to breast and ovarian cancer, and these findings raise the possibility that changes in chromosome segregation or gene expression might contribute to the increased cancer risk associated with these mutations." (PMID 29447171, 2018). "Likewise, several observations in breast cancer patients led to the hypothesis that low‐penetrance cancer susceptibility polymorphisms act as modifier genes in BRCA1/BRCA2 mutation carriers and non‐carriers to increase cancer risk." (PMID 29507082, 2018). "Secondly, GSTP1 functions as a caretaker gene with its loss resulting in increased oxidative DNA damage and mutagenesis, thus, in BRCA2 deficient cancers already sensitive to oxidative stress, any loss of GSTP1 may have a more pronounced effect and be integral in tumour development." (PMID 28893223, 2017). "Overall, significantly less OC cases are seen in PALB2 families when compared with BRCA1 and BRCA2 families; therefore, it seems that PALB2 may contribute in a different way than BRCA1 and BRCA2 to cancer predisposition, possibly as a result of PALB2 distinct roles in DDR." (PMID 28858227, 2017). "The meta-analysis suggests that the BRCA2 rs144848 polymorphism may play a role in cancer risk." (PMID 28418854, 2017).